MAPT (microtubule associated protein tau)
Diseases named in the same sentence as MAPT in open-access papers (continued):
Sharing a sentence is not in itself a finding about the gene and the disease.
Alzheimer disease (continued). "In the same study the authors evaluated the methylation profiles of MAPT promoter in the frontal cortex and hippocampus of controls, Alzheimer's disease patients, PD patients, and subjects with other tauopathies and synucleinopathies." (PMID 22623900, 2012). "We sequenced exons 1, 2 and 9–13 of MAPT in 59 Finnish patients with FTLD and analysed the MAPT haplotypes in these patients, 122 patients with early onset Alzheimer's disease (eoAD, age at onset before 65 years) and 198 healthy middle-aged controls." (PMID 19091059, 2008). "Alzheimer's disease (AD) is characterized by abnormalities in post-translational processing of two proteins, the amyloid precursor protein (APP) and the microtubule associated protein tau." (PMID 17183681, 2006). "We spatially multiplexed the proteome geography at two levels of the cortex and the subcortical white matter in patients with various types of dementia (Alzheimer’s disease, C9orf72, MAPT also referred to as FTLD-tau, FTLD-TDP, FTLD-GRN; n = 6 per syndrome) and neurologically healthy controls (NHC)." (PMID 40476255, 2025). "SNHG8 was significantly reduced in FTLD-tau caused by MAPT IVS10 + 16 or p.P301L; a primary sporadic tauopathy, progressive supranuclear palsy; and a secondary tauopathy, Alzheimer’s disease." (PMID 37730840, 2023). "In Alzheimer's disease (AD), GSK3β phosphorylates tau protein (MAPT), leading to its dissociation from microtubules and increasing its propensity to aggregate, which results in the formation of neurofibrillary tangles, one of the most prominent features of the disease." (PMID 37288744, 2023). "Similarly, no Braak-stage-dependent changes were observed for expression of Alzheimer disease genes APP (CPM = 557, TPM = 7616, PE = 100%) or microtubule associated protein tau (MAPT; CPM = 732, TPM = 12, PE = 100%)." (PMID 35813880, 2022). "Finally, as a convincing proof of principle, Tau (MAPT) shifts from a general cytoskeletal pattern in control samples towards a large presence in Fraction 6 in Alzheimer’s disease tissue, which contains large protein complexes such as ribosomes." (PMID 35611312, 2022). "Finally, given the human-specific nature of Tau-related disorders such as Alzheimer’s disease and the broad interspecies variability of the MAPT gene and the regulation of its alternative splicing events, we will only dwell on human Tau isoforms." (PMID 35269461, 2022). "Additionally, the results of the present study suggest that some signature proteins in the cingulate cortex cluster participate in the pathogenesis of some neurological diseases, such as MAPT in Alzheimer’s disease and SYUA in Parkinson’s disease." (PMID 34763096, 2022). "Interestingly, AKT1, MAPK8, BCL2L1, FOXO3, and CTNNB1 were not only significantly associated with pathogenic genes (APP, MAPT, and PSEN2) but also with longevity in Alzheimer’s Disease." (PMID 36620771, 2022). "As a result, the regional distribution of MAPT protein in the brain may be very important, especially for Alzheimer’s disease studies." (PMID 33952343, 2021). "It has been hypothesized that the reduction of MAPT would result in depolymerizing neurofibrillary tangles and could be a potential strategy for the treatment of Alzheimer’s disease and other tauopathies." (PMID 32575375, 2020). "However, ASOs (developed by Ionis) targeting tau (MAPT) are being studied in a phase I clinical trial for Alzheimer’s disease." (PMID 32914362, 2020). "In a study of >20,000 individuals from Mayo Clinic and the Alzheimer's Disease Genetics Consortium (ADGC), we identified associations with both reduced AD risk and reduced brain MAPT levels with the H2 haplotype." (PMID 32400971, 2020). "The magnitude of episodic memory impairment can mirror that of Alzheimer's disease (AD), and therefore it is not uncommon for clinical AD to be diagnosed initially in some patients with MAPT mutations." (PMID 31870644, 2020).
Alzheimer disease (continued). "In MAPT mutation carriers, tracer uptake was seen primarily (though not exclusively) in mutations with Alzheimer’s disease-like tangles." (PMID 30704514, 2019). "However, tau tracer binding was detected in the FTDP-17 case with a R406W MAPT mutation (case FTDP1), which produces pathological inclusions that closely resemble those found in Alzheimer’s disease." (PMID 29716656, 2018). "These include Parkinson's and Alzheimer's disease, amyotrophic lateral sclerosis (ALS) and Parkinsonian disorders e.g., progressive supranuclear palsy, all of which have been linked to polymorphisms in the microtubule stabilizing protein TAU (MAPT)." (PMID 30135644, 2018). "For tauopathies like Alzheimer’s disease, involving aggregations of paired helical filaments of MAPT into neurofibrillary tangles, USP9 may therefore warrant further study as a target for the development of new intervention strategies." (PMID 27878758, 2017). "Mutations in MAPT gene are described in neurodegenerative disorders such as Alzheimer’s disease; therefore, it is highly likely that the duplicated region of MAPT could be involved in the phenotype of 17q31.21 duplication patients." (PMID 28496102, 2017). "More recently, we found that 71% of these Basque GRN carriers also carry a rare variant in the microtubule-associated protein tau gene (MAPT) in exon 7 (p.A152T), which has been linked to risk for both FTD-spectrum disorders and clinical Alzheimer’s disease (AD)." (PMID 28594853, 2017). "We provide evidence for how previously identified GWAS loci for schizophrenia (NRGN), Parkinson’s disease, and Alzheimer’s disease (PARK16 and MAPT loci) could increase the risk for disease at a molecular level." (PMID 27287230, 2016). "Interestingly, best known for their association with Alzheimer’s disease, amyloid precursor protein (APP) and the microtubule-associated protein tau (MAPT) were elevated in maters." (PMID 23874981, 2013). "Expression of two genes in particular, amyloid beta (A4) precursor protein (APP) and microtubule associated protein tau (MAPT), which are normally associated with Alzheimer’s Disease, was found to be significantly higher in the maters relative to the non-maters." (PMID 23874981, 2013). "Interestingly, MAPT mutations do not give rise to Alzheimer’s Disease, underscoring the preceding role of amyloid-β deposition in the pathogenesis of Alzheimer’s." (PMID 40969213, 2025). "Pathological accumulation of the microtubule-associated protein tau is closely associated with cognitive decline in Alzheimer’s disease (AD), and with other tauopathies, such as frontotemporal lobar degeneration-tau (FTLD-tau), which can be directly caused by mutations in the tau gene, MAPT." (PMID 38890273, 2024). "The brains of patients with tauopathies, such as Alzheimer’s disease, frontotemporal lobar degeneration (FTLD), Pick’s disease, corticobasal degeneration, or progressive supranuclear palsy, show protein aggregates of the microtubule-associated protein tau (also known as MAPT)." (PMID 37834443, 2023). "In contrast, peptides deriving from microtubule-associated protein tau, presenilin 2 and serine/threonine-protein kinase TBK1 were exclusively reported to bind MHC molecules encoded by the HLA-DRB1 1501 allele, a recently-identified susceptibility gene for late onset Alzheimer's disease." (PMID 31824497, 2019). "Whereas most tauopathies such as Pick's disease, corticobasal degeneration, progressive supranuclear palsy and Alzheimer's disease (AD) are not linked to mutations, frontotemporal dementia with parkinsonism linked to chromosome 17 is caused by autosomal dominant mutations in the MAPT gene." (PMID 24905733, 2014). "A mouse model used to study Alzheimer’s disease, they express three human transgenes: PS1M146V, APPSwe, and MAPT." (PMID 41209083, 2025).
Alzheimer disease (continued). "In Alzheimer’s disease, the thalamus and basal ganglia exhibit significant atrophy, and recent transcriptomic analyses have shown that genes such as APOE, MAPT, and PSEN1 are differentially expressed in these regions." (PMID 41142949, 2025). "Future studies should evaluate the long-term effects of MAPT-ASO treatment on neuronal connectivity and synaptic function, as well as its efficacy in in vivo models of Alzheimer’s disease." (PMID 41373505, 2025). "This is particularly evident in the Alzheimer’s disease pathway, where key genes involved in amyloid processing and tau protein pathology, such as APP and MAPT, exhibit significant increases in expression." (PMID 38927081, 2024). "In the pathway unification database, SRC, EGFR, MAPT, APP and PRKCA were identified as key molecules in the pathway of Alzheimer’s disease." (PMID 37010714, 2023). "Based on the literature survey and Uniport database findings, this article focuses on the effects on the protein folding and degradation system and Alzheimer’s disease when the molecular network consisting of BAG2, HSC70, STUB1 and MAPT is dysregulated." (PMID 37251806, 2023). "Interestingly, the authors also detected a significant increase in the TIR-MAPT/total MAPT mRNA ratio when comparing Alzheimer’s Disease Braak Stage VI patients to healthy controls, highlighting that this novel mRNA species could be strongly correlated with neurodegenerative processes." (PMID 36499709, 2022). "These proteins include tau (MAPT) and alpha-synuclein (SYUA), which are important biomarkers for Alzheimer’s disease and Parkinson’s disease, respectively." (PMID 34763096, 2022). "Similarly, the ratio of alternatively spliced products of the tau gene product MAPT, namely 3R tau (formed upon exclusion of exon 10) and 4R tau (formed upon inclusion of exon 10) contribute to another well-known neurodegenerative disorder, Alzheimer’s disease (AD)." (PMID 34769301, 2021). "The rostral distribution of the MAPT ASO to the cranium is important because this target is important in frontotemporal dementia and Alzheimer’s disease, both neurodegenerative diseases of the brain." (PMID 32771027, 2020). "The resulting transgenic mouse model, Alzheimer’s disease-like pathology with APP, PSEN1, and MAPT transgenes (ADLPAPT), exhibited Aβ accumulation, NFTs, early neuronal loss in the brain, and subsequent memory impairments." (PMID 29338754, 2018). "One of the neuropathological hallmarks of Alzheimer's Disease (AD) is the neurofibrillary tangle, which contains paired helical filaments (PHFs) composed of hyperphosphorylated forms of the microtubule-associated protein tau (MAPT) by mechanism which is not illustrated." (PMID 28415654, 2017). "In addition to Alzheimer’s disease, tau inclusions composed of both 3R-tau and 4R-tau isoforms occur also in several other disorders such as postencephalitic parkinsonism, chronic traumatic encephalopathy, Parkinson-dementia complex of Guam, and FTDP-17 due to MAPT mutations." (PMID 27358064, 2016). "Recently, the Ibero-American Alzheimer Disease Genetics Group Researchers analyzed the coding region and flanking sequences of APP, PSEN1, PSEN2, MAPT, and GRN by pooled-DNA exon sequencing in 167 clinical and five autopsy-confirmed, mainly EOAD cases." (PMID 25914626, 2015). "Specific TRA2B-related splicing processes have been implicated in human diseases like spinal muscular atrophy (splicing of SMN) and in tauopathies like Alzheimer’s disease and FTDP-17 (splicing of MAPT)." (PMID 24586484, 2014). "MAPT exons 1, 2 and 9–13 were sequenced in 59 patients with FTLD, and MAPT haplotypes were analysed in these patients, 122 patients with early onset Alzheimer's disease (eoAD) and 198 healthy controls." (PMID 19091059, 2008). "Regardless of its etiology, Alzheimer disease is riddled with signs of impaired lysosomal function: In healthy neurons, lysosomes clear β-amyloid, phospho-MAPT/Tau aggregates, and dysfunctional organelles." (PMID 41103078, 2025).
Alzheimer disease (continued). "Similarly, as in Alzheimer’s disease (AD), PSP pathogenesis involves the joint expression of specific N- and C-terminal MAPT isoforms." (PMID 40362170, 2025). "In CN samples, interestingly, among the most significant pathways enriched with significant CpGs is the KEGG pathway “Alzheimer’s disease”, which was curated based on recent AD literature and included genes that confer AD risks, such as APOE, PSENEN, MAPT, CALM3, MME, and others." (PMID 37038196, 2023). "Given the strong genetic correlation between Alzheimer’s disease and Schizophrenia, it is not surprising that we found a positive correlation for MAPT’s colocalization in the Schizophrenia dataset." (PMID 37907504, 2023). "Interestingly, a preferential expression of MAPT exon 10, promoted by the STOX1A transcription factor which is involved in late-onset Alzheimer’s disease, is observed in glial cell cultures." (PMID 36675972, 2022). "The MAPT gene is involved in dozens of neurodegenerative diseases called tauopathies, including frontotemporal lobar degeneration/frontotemporal dementia (FTLD/FTD) and Alzheimer’s disease (AD)." (PMID 34993155, 2021). "MAPT encodes the microtubule-associated protein tau known to associate with multiple neurodegenerative diseases including Alzheimer’s disease (MIM: 104300) and Parkinson’s disease (MIM: 605909) and balance of MAPT isoforms is critical for neuronal normal functioning." (PMID 33539344, 2021). "It has been reported that the splicing of the APP, APOE, SNCA, MAPT, DAO, SHANK3, and CACNA1C genes, which are recorded in the PsyGeNET database, were abnormal in patients with neurological diseases such as Parkinson’s disease, Alzheimer’s disease, and amyotrophic lateral sclerosis." (PMID 39858933, 2025). "In contrast, the genetics of MAPT (MIM# 157140) did not connect to Alzheimer’s disease." (PMID 34718566, 2022). "In single and double KI rats total MAPT and 4RMAPT protein levels are unchanged over time; the expression of the 3RMAPT isoform decreases and the Alzheimer’s disease-relevant AT100 phosphorylation, which is absent at 14 weeks of age in wildtype, single and double KI rats increases with age." (PMID 33076948, 2020). "Since MAPT becomes hyperphosphorylated and aggregates in the neurons of Alzheimer’s disease brains, we would expect this to reduce the available APP on the neuronal plasma membrane and so reduce iron export in aged neurons showing Alzheimer’s disease pathology." (PMID 30150923, 2018). "This revealed tracer binding to tissue from cases with Alzheimer’s disease and the FTDP-17 case with the R406W MAPT mutation, but not to cases with Pick’s disease, progressive supranuclear palsy, corticobasal degeneration, and FTDP-17 with Δ280K or 10 + 16 MAPT mutation." (PMID 29716656, 2018). "Next, we assessed the transcriptome of genes of interest to Alzheimer’s disease and resistance, APOE, APP, MAPT, PSEN1, and RELN and found no notable differences across cell lines." (PMID 38571814, 2024). "Alzheimer disease (AD) is characterized by senile plaques comprised primarily of β-amyloid (Aβ) and hyperphosphorylated tau in the form of neurofibrillary tangles; however, the largest AD GWAS have not shown a genetic signal in the regions of APP or MAPT in late-onset AD." (PMID 31261387, 2019).
tauopathies (475 papers, 2007 to 2026). "The microtubule-associated protein tau (MAPT) undergoes age-associated alternative splicing of exon 10 to generate 3R and 4R isoforms, and disruption of the 4R:3R ratio is a central feature of tauopathies." (PMID 41646425, 2026). "Mitochondrial dysfunctions contribute to the pathogenesis of tauopathies, a group of neurodegenerative diseases with abnormal accumulation of microtubule-associated protein tau." (PMID 42195281, 2026). "The microtubule-associated protein Tau (encoded by the MAPT gene) is linked to a family of neurodegenerative disorders defined as tauopathies, which are characterized by its brain accumulation in neurofibrillary tangles and neuropil threads." (PMID 40319030, 2025). "MAPT, a hallmark of tauopathies, was centrally positioned in this network, forming directional links with kinase regulators and phosphatase-associated modules." (PMID 40665052, 2025). "Tauopathies represent a diverse group of neurodegenerative disorders characterized by the abnormal aggregation of the microtubule-associated protein tau." (PMID 40082954, 2025). "Microtubule dysregulation is strongly associated with accumulation of the microtubule-associated protein tau in tauopathies, and most LRRK2 cases with pathogenic mutations harbor Alzheimer’s type tau pathology." (PMID 40425780, 2025). "Microtubule-associated protein tau assembles into highly ordered amyloid filaments in a subset of neurodegenerative diseases, termed tauopathies." (PMID 39880096, 2025). "In conclusion, mutations in MAPT can give rise to cases of FTDP-17 that resemble sporadic tauopathies, including Pick’s disease and AGD." (PMID 40044789, 2025). "Primary tauopathies result from direct mutations in the microtubule-associated protein tau (MAPT), a protein critical for microtubule stabilization and intracellular transport." (PMID 40799762, 2025). "The accumulation of microtubule-associated protein tau (MAPT) in intracellular fibrillary deposits is a neuropathological hallmark of tauopathies." (PMID 41023457, 2025). "Since then, more mutations in MAPT have been identified and linked to other primary tauopathies such as Pick’s disease, PSP and CBD, including R5L, K257 T, P301L, P301S, S305 N, V337M, and R406 W." (PMID 40349043, 2025). "Mutations in MAPT have been shown to cause tauopathies, reinforcing tau’s critical role in AD pathology." (PMID 40076442, 2025). "In the first, MAPT mutations associated with a 4R tauopathy were selected from the literature based on their potential to interfere with known tau fibril conformations." (PMID 40780308, 2025). "In some studies, certain MAPT variants associated with an increased risk of tauopathies, likely due to increased MAPT expression." (PMID 40589526, 2025). "The iPSC line BA‐001.1, of Babur ancestry, was selected to introduce one of two well‐characterized MAPT mutations—P301L or R406W—both of which are associated with frontotemporal lobar degeneration and other tauopathies." (PMID 40219788, 2025). "Tauopathies, a group of neurodegenerative diseases characterized by abnormal aggregation of the microtubule-associated protein tau include AD, progressive supranuclear palsy (PSP), corticobasal degeneration (CBD), and Pick’s disease." (PMID 41462898, 2025). "Current research on MAPT mutations primarily focuses on small nucleotide polymorphisms (SNPs) that lead to tauopathies and synucleinopathies." (PMID 40725212, 2025). "In this study, for the first time, iPSCs carrying the p.N279K genetic variant of the MAPT gene were utilised to create a test model for studying mitochondrial biogenesis alterations caused by tauopathy." (PMID 40149527, 2025). "We have developed a series of targeted mice expressing frontotemporal-dementia-causing mutations in the humanized MAPT gene to investigate the earliest stages of tauopathy." (PMID 39719507, 2025).